MUC1 (mucin 1, cell surface associated)
Diseases named in the same sentence as MUC1 in open-access papers (continued):
Sharing a sentence is not in itself a finding about the gene and the disease.
mucinous ovarian tumors (2 papers, 2019 to 2021). "As to MUC1, high apical expression was associated with non-mucinous ovarian tumors, and low expression of MUC1 in the apical membrane was reported to be associated with early stage and good outcome for invasive tumors." (PMID 34641504, 2021).
mucoepidermoid carcinoma (2 papers, 2022 to 2023). A carcinoma morphologically characterized the presence of cuboidal mucous cells, goblet-like mucous cells, squamoid cells, cystic changes, and a fibrotic stromal formation. "The results show that MUC1 is intensely expressed in salivary duct carcinoma, which is known for its aggressive growth and low survival rates while MUC16 shows the highest intensity in mucoepidermoid carcinoma." (PMID 35389164, 2022).
nematode infection (2 papers, 2013 to 2025). "In contrast to clearance of nematode infection, onset of clearance of C. rodentium was preceded by an early increase in Muc1, Muc2, Muc4 and Muc13 mucin transcript levels that had returned to pre-infection levels at least four days prior to clearance." (PMID 24386378, 2013). "Also unique to this GO term was the upregulated gene sialic acid binding Ig like lectin 1(SIGLEC1) which is activated in monocytic cells to interact with the gene mucin 1 (MUC1); a gene shown to respond during GI nematode infections." (PMID 40906414, 2025).
oral cancer (2 papers, 2011 to 2024). "Notably, investigations have shown that CRISPR/Cas9 can effectively target the gene MUC1 (Mucin short variant S1), which is frequently overexpressed in oral cancer cells." (PMID 38915370, 2024). "Targeting MUC1 using CRISPR/Cas9 has demonstrated a significant reduction in the growth and proliferation of oral cancer cells." (PMID 38915370, 2024).
ovarian serous cystadenocarcinoma (2 papers, 2017 to 2021). A malignant serous cystic epithelial neoplasm arising from the ovary. "As to OV(Ovarian serous cystadenocarcinoma), A product of the MUC1 gene of the genes selected by our method has been used as a marker for different cancers." (PMID 34149811, 2021). "MUC1 copy gain state predominates for several cohorts of BRCA, stages I and II of ovarian serous cystadenocarcinoma (OSC), and stage II UEC." (PMID 28978023, 2017).
Pancreatic cysts (2 papers, 2018 to 2024). A cyst of the pancreas that possess a lining of mucous epithelium. "Mucin (MUC) genes, such as MUC1 and MUC2, are associated with different types of pancreatic cysts, with MUC2 typically expressed in IPMNs and MUC1 associated with more aggressive cystic neoplasms." (PMID 39200786, 2024).
polyp (2 papers, 2010 to 2017). A usually exophytic mass attached to the underlying tissue by a broad base or a thin stalk. "MUC1 was uniformly expressed in the cytoplasm of the crypt epithelial cells in adjacent normal colon as well as in polyp lesions." (PMID 27705923, 2017). "Using the model with the negative log-log link to build the ordinal regression, the grade of glandular dysplasia was found to be significantly associated with the three variables of expression levels of MUC1 and MUC2, and polyp site." (PMID 20929551, 2010). "Considering the high clinical utility of the appropriate polyp classification, in this study, we evaluated the potential of colonic mucins (MUC1, MUC4, MUC17, MUC2, MUC5AC, and MUC6) and associated glycans (Tn/STn-MUC1 and CA19-9) for differentiating SSA/P from HP and TA." (PMID 27705923, 2017). "The expression of MUC1, MUC5AC, Tn/STn-MUC1, and CA19-9 were significantly increased in all types of polyp lesions (p < 0.0005) compared to adjacent normal colon (NC)." (PMID 27705923, 2017). "In both adjacent normal colon and polyp subtypes, cytoplasmic expression of MUC17 and Tn/STn-MUC1 was observed in crypt epithelial cells." (PMID 27705923, 2017).
preeclampsia (2 papers, 2013 to 2021). Preeclampsia is a hypertensive disorder of pregnancy that is characterized by new-onset hypertension with proteinuria presenting after 20 weeks of gestation, and depending on mild or severe forms may initially present with severe headache, visual disturbances, and hyperreflexia. "In particular, loss of heavily O-glycosylated MUC1 in human placenta is associated with inflammation in pregnancies affected by preeclampsia and choriamnionitis." (PMID 33916770, 2021). "In humans, MUC1 is overexpressed in severe preeclampsia, and its overexpression suppresses trophoblast cell invasion." (PMID 24265769, 2013). "MUC1 is also expressed in mouse trophoblast cells and its expression is regulated by peroxisome proliferator-activated receptor γ (PPAR-γ), which is linked to preeclampsia in humans and rats." (PMID 33916770, 2021).
retinoblastoma (2 papers, 2016 to 2024). A malignant tumor that originates in the nuclear layer of the retina. "For example, the aptamer-DOX conjugates EpDT3-Dox, HER2-Dox, MUC1-Dox and PSMA-Dox were successfully used in the treatment of retinoblastoma, breast, lung, and prostate cancers, respectively." (PMID 26808385, 2016).
soft tissue sarcoma (2 papers, 2021 to 2022). A malignant neoplasm arising from muscle tissue, adipose tissue, blood vessels, fibrous tissue, or other supportive tissues excluding the bones. "Recently, the potential mechanism of miR-1226-3p regulating MUC1 which, in turn, affects resting of dendritic cells, was shown to play an important role in soft tissue sarcoma (STS) recurrence." (PMID 35163222, 2022). "Seven genes (LPP‐AS2, MUC1, GAB2, hsa‐let‐7i‐5p, hsa‐let‐7f‐5p, hsa‐miR‐101‐3p, andhsa‐miR‐1226‐3p) in a recurrent soft tissue sarcoma‐specific ceRNA network associated with recurrence and survival were identified based on the TCGA database." (PMID 34196116, 2021).
T cell lymphoma (2 papers, 2016 to 2023). "Imprime significantly enhanced the activity of an anti-MUC1 tumor-targeting antibody in a syngeneic T cell lymphoma model engineered to express the cell surface protein MUC1." (PMID 27812183, 2016). "A chimeric bovine papillomavirus (BPV) VLPs displaying MUC1 induced MUC1-specific CTL in a human MUC1 transgenic mouse model and impaired, or eradicated in few mice, tumor growth induced by RMA-MUC1 cells (a T cell lymphoma line) in this mouse model." (PMID 37629147, 2023).
tongue cancer (2 papers, 2020 to 2023). A malignant neoplasm affecting the tongue. "We selected three cell lines, OME (an immortalized epithelial cells lines with low expression of MUC1 was used as the control group), HN4 (oropharyngeal carcinoma cell line), and Cal33 (tongue carcinoma cell line with high expression of MUC1 were used as the experimental groups)." (PMID 31800160, 2020).
vascular tumor (2 papers, 2021 to 2024).
villous adenoma (2 papers, 2010 to 2021). An epithelial neoplasm morphologically characterized by the presence of a villous architectural pattern. "Colonic villous adenoma-like growth pattern and immunohistochemical profile of MUC2-, MUC5AC- and CDX2-positivities but MUC1- and MUC6-negativities in the present case indicated that the lesion was consistent with the intestinal type IPMN." (PMID 34674710, 2021). "While the highest expression of MUC1, and MUC6 was observed in villous adenomas, they were totally absent in hyperplastic polyps." (PMID 20929551, 2010).
acne (1 paper, 2021). An inflammatory process of the sebaceous glands which is characterized by comedones, nodules, papules and/or pustules on the skin. "Variations in MUC1 may influence the anti-bacterial properties of the glycoprotein, thus influencing acne development." (PMID 33849530, 2021).
adenocarcinoma in situ (1 paper, 2018). A lesion in which the normally situated glands are partially or completely replaced by atypical cells with malignant characteristics. "In the adenocarcinoma lesions, MUC1 expression was increased in adenocarcinoma versus adenocarcinoma in situ, although not significantly (mean difference = 0.20, 95% CI, −0.055-infinity; P = 0.094)." (PMID 30479696, 2018). "Among adenocarcinoma lesions, MUC1 expression levels were increased in adenocarcinoma versus adenocarcinoma in situ (AIS), although not significantly (mean difference = 0.20, 95% CI, −0.055 to infinity, P = 0.094)." (PMID 30479696, 2018).
Airway obstruction (1 paper, 2020). Obstruction of conducting airways of the lung. "The levels of cell-bound MUC1 expression in basal cells and in soluble MUC1 in bronchial wash were increased in smokers, regardless of airway obstruction." (PMID 32948202, 2020).
Alzheimer disease (1 paper, 2024). A progressive, neurodegenerative disease characterized by loss of function and death of nerve cells in several areas of the brain leading to loss of cognitive function such as memory and language. "Whether the observed negative correlation between MUC1 and activated CD4 T cells in Alzheimer’s disease patients is valid, warrants further investigation." (PMID 38711596, 2024).
aphthous ulcers (1 paper, 2025). "However, MUC1, encoded by the most highly induced mucin gene in aphthous ulcers, was shown also to provide an inducible portal for bacterial uptake." (PMID 40386941, 2025).
autosomal dominant polycystic kidney disease (1 paper, 2023). Autosomal dominant form of polycystic kidney disease. "Given this atypical presentation, we debated the likelihood of a de novo autosomal dominant polycystic kidney disease (ADPKD) or an autosomal dominant tubulointerstitial kidney disease (UMOD, MUC1), as well as bilateral medullary sponge kidneys." (PMID 37801220, 2023).
bacterial vaginosis (1 paper, 2016). Infection caused by bacterial overgrowth in the vagina. "In this study we report the changes in membrane bound (MUC1 and MUC4) and gel-forming mucins (MUC5AC and MUC7) relative to the influence of hormones and the presence of the abnormal vaginal flora of bacterial vaginosis." (PMID 27437931, 2016).
Bartter syndrome (1 paper, 2025). "The median coverages in the VNTR region of MUC1 were 363 in cases of suspected hereditary nephrotic syndrome, 340 in cases of suspected Bartter syndrome, 318 in cases of suspected Dent disease, and 304 in cases of suspected hereditary renal tubular acidosis." (PMID 40244446, 2025).
bile duct tumors (1 paper, 2014). "However, recent molecular biological studies suggested the correlations of the expression of MUC-1 and MUC-2 mucin antigens with the prognosis of intrahepatic bile duct tumors." (PMID 24727803, 2014).
bipolar disorder (1 paper, 2020). A disorder of the brain that causes unusual shifts in mood, energy, activity levels and the ability to carry out day-to-day tasks. "By performing whole genome sequencing analysis of a family in which bipolar disorder and ADTKD co-segregate, we identified the E492K mutation of NTRK1 that is linked with MUC1 and co-segregates with these two diseases." (PMID 33235206, 2020).
brain cancer (1 paper, 2024). A primary or metastatic malignant neoplasm affecting the brain. "Notably, genes linked to brain cancer progression and tumor immunity (ENO1, MUC1, COL5A1, and IL11) were significantly downregulated (>2-fold) in KO brain tissue but were upregulated in FABP7 OV astrocytes." (PMID 39596296, 2024). "We also found that the expression of the onco-immune factors (ENO1, MUC1, COL5A1, IL11) that we identified was significantly correlated with FABP7 expression in patient brain cancers, particularly LGG, suggesting the pathological relevance of the results of our transcriptomic analyses." (PMID 39596296, 2024).
bronchiolitis (1 paper, 2023). Inflammation of the bronchioles characterized by swelling of the bronchioles and mucus accumulation. "Deep sputum samples were collected from children with bronchiolitis infected with primary RSV, and the levels of MUC1 and pro-inflammatory factors were evaluated." (PMID 38036963, 2023). "In this study, we primarily found that the MUC1 protein levels, as well as TNF-α levels, were significantly up-regulated in the sputum of children with RSV-infected bronchiolitis during the exacerbation period." (PMID 38036963, 2023).
bronchioloalveolar carcinoma (1 paper, 2023). A well or moderately differentiated morphologic variant of lung adenocarcinoma characterized by tumor growth along the alveolar structures without stromal, vascular, or pleural invasion. "Decreased polarized and increased depolarized MUC1 expression was significantly associated with the progression from atypical adenomatous hyperplasia through bronchioloalveolar carcinoma to mixed types." (PMID 36367122, 2023).
central obesity (1 paper, 2021). "Their results indicated that MUC1 and its nearby gene region may play a critical role in determining blood pressure status and central obesity." (PMID 34638981, 2021).
cervical adenocarcinoma (1 paper, 2024). An adenocarcinoma arising from the cervical epithelium. "Patients with cervical adenocarcinoma and high MUC1 expression have a low survival rate and lymph node metastasis." (PMID 38702644, 2024).
cervical intraepithelial neoplasm (1 paper, 2024). "More than half of the cervical intraepithelial neoplasm (CIN) tissues exhibited MUC1 expression (30/51, 58.8%)." (PMID 38702644, 2024).
Chronic tubulointerstitial nephritis (1 paper, 2023). Chronic inflammation of the kidney affecting the interstitium of the kidneys surrounding the tubules. "Secondly, alleles with longer VNTR (>55 repeats) in exon 2 of MUC1 have been linked to increased levels of serum urea und serum urate as biomarkers for reduced kidney function and with the risk for chronic tubulointerstitial nephritis as opposed to shorter VNTRs." (PMID 37316299, 2023).
dermatitis (1 paper, 2026). An inflammatory process affecting the skin. "This patient exhibited transient dermatitis with localized MUC1 and CD3 staining, as potential evidence of on-target, off-tumor T cell reactivity, perhaps contributing to disease stabilization." (PMID 42274746, 2026).
disc degeneration (1 paper, 2017). "Here we present the first data for the constitutive presence of MUC1 in the human disc, and its altered expression during disc degeneration." (PMID 28482827, 2017). "Our novel findings here with MUC1 and its increasing expression during disc degeneration point to the importance of future work which focuses upon interactions of MUC1 with major cytokines and chemokines in the degenerating disc." (PMID 28482827, 2017). "This is the first study describing the constitutive presence of MUC1 in the human disc, and its increased expression during disc degeneration, and its in vitro downregulation during exposure to the proinflammatory cytokines IL-1ß and TNF-α." (PMID 28482827, 2017). "Little is currently known about the presence or role of MUC1 in human disc degeneration." (PMID 28482827, 2017).
duodenal cancer (1 paper, 2024). "This case suggests a possible beneficial effect of adoptive cell therapy with WT1/MUC1-DC and CAT for peritoneal dissemination and malignant ascites in duodenal cancer." (PMID 39737308, 2024). "We report a case in which the combination of a WT1/MUC1-DC vaccine and CAT was highly efficacious in the treatment of unresectable duodenal cancer with peritoneal dissemination and malignant ascites that had proven refractory to chemotherapy." (PMID 39737308, 2024). "Therefore, the combination of WT1/MUC1-DC and CAT may enhance the antitumor immune response to duodenal cancer." (PMID 39737308, 2024).
duodenum (1 paper, 2019). "One limitation of our study is that we have not administered nab‐paclitaxel to patients whose ampullary and duodenum adenocarcinomas are negative for both CK7 and MUC1." (PMID 31102323, 2019).
endocervical adenocarcinoma (1 paper, 2006). An adenocarcinoma that arises from the endocervix. "The objectives of this study were to evaluate a panel of monoclonal antibodies (MUC1, p16, ER, PR, and vimentin), and assess their diagnostic value in distinguishing between primary endocervical adenocarcinoma (ECA), and primary endometrial mucinous adenocarcinoma (EMMA)." (PMID 16409624, 2006). "Though the physiological role of MUC1 in the female genital tract and its expression in endometrial hyperplasia and carcinoma have been investigated, the utility of MUC1 in differential diagnosis of endocervical adenocarcinoma and endometrial mucinous adenocarcinoma has been little explored." (PMID 16409624, 2006).
enterocolitis (1 paper, 2025). An inflammatory process affecting the small intestine and colon. "MUC1 is often upregulated during enterocolitis and may contribute to epithelial proliferation and inflammation, while MUC2, secreted by goblet cells, is vital for maintaining the mucosal barrier and microbial homeostasis." (PMID 40431496, 2025).
extramammary Paget disease (1 paper, 2019). A malignant neoplasm in which there is infiltration of the skin by neoplastic large cells with abundant pale cytoplasm and large nuclei with prominent nucleoli (Paget cells). "Notably, EMA (also called MUC1) is universally expressed by nearly all cases of extramammary Paget’s disease and it is comparable with CK7 as a universal cytokeratin marker for Paget’s cells." (PMID 29542074, 2019).
gastric diseases (1 paper, 2013). "As we know, PGC, MUC1, MUC2, the three proteins had solely important diagnostic role for the gastric disease." (PMID 23937908, 2013). "As physiologically functional gastric proteins and “ectopic” expressed protein, the association of PGC, MUC1 and MUC2 solely and gastric diseases had been reported in the past." (PMID 23937908, 2013). "Phenotypes of PGC, MUC1 and MUC2 co-expression in dynamic gastric diseases are variable." (PMID 23937908, 2013). "We aimed to investigate the co-expression of PGC, MUC1 and MUC2 which might also give a clue for the understanding of the progression of gastric diseases." (PMID 23937908, 2013).
gastroenteritis (1 paper, 2008). An inflammatory disorder that affects the upper and lower gastrointestinal tract. "Consistent with an important role for Muc1 upregulation in the intestine limiting infection, Muc1−/− mice have a higher rate of systemic infection in a murine Campylobacter jejuni model of gastroenteritis." (PMID 19088856, 2008).
glomerular disorder (1 paper, 2021). A disease involving the renal glomerulus. "However, in this family, the index of suspicion is low for MUC1-associated disease given the clinical characteristics consistent with a primary glomerular disorder as evidence by > 3 g/day of protein excretion and supported by pathologic findings rather than a primary tubulointerstitial process." (PMID 34565340, 2021).
GNE myopathy (1 paper, 2021). "Our results showed that MUC1 and KL‐6 existed in RVs of GNE myopathy and sIBM." (PMID 33225515, 2021).
Hypercalciuria (1 paper, 2025). "Alterations in the calcium channel transient receptor potential cation channel subfamily V member 5 (TRPV5) and the glycoprotein mucin-1 (MUC1) have been associated with both hypercalciuria, which predisposes individuals to kidney stones, and tumor progression." (PMID 41182764, 2025).
hyperplastic polyp (1 paper, 2010). A polyp found mainly in the stomach and colon. "The fact is that the pattern of expression of MUC1, MUC2, and MUC6 that is reported in the present article for hyperplastic polyps, is identical to what is reported in other studies for normal mucosa." (PMID 20929551, 2010).
infectious colitis (1 paper, 2008). A viral or bacterial infectious process affecting the large intestine. "Human biopsies used for investigating MUC1 induction in infectious colitis." (PMID 19088856, 2008).
inflammatory breast carcinoma (1 paper, 2024). An advanced, invasive breast adenocarcinoma characterized by the presence of distinct changes in the overlying skin. "Quantum dots were conjugated with calcitriol and MUC-1 antibodies to target inflammatory breast cancer (IBC) cells." (PMID 38730959, 2024).